CRP (C-reactive protein)
Diseases named in the same sentence as CRP in open-access papers (continued):
Sharing a sentence is not in itself a finding about the gene and the disease.
mucinous neoplasm (5 papers, 2021 to 2025). "A significant association was also seen between high CRP levels and a mucinous tumour type in the U-CAN validation cohort." (PMID 39613865, 2024). "In the U-CAN validation cohort, a high CRP level was strongly associated with high tumour grade 6, and with mucinous tumour type." (PMID 39613865, 2024). "CRP and IL-6 levels among inflammatory markers were significantly higher in the mucinous neoplasm group." (PMID 41451009, 2025). "Patients treated with scRT were older and had less advanced tumours (cT1-3, cN0, cMRF-, or cEMVI-) according to treatment indication, and had fewer mucinous tumours and shorter tumour lengths, but higher C-reactive protein (CRP) levels." (PMID 36551723, 2022). "Computed tomography revealed a markedly tense appendiceal mucinous tumor with surrounding inflammation, and laboratory test results showed elevated serum C-reactive protein (7.47 mg/dL), indicating impending rupture of the appendix." (PMID 33609942, 2021).
obsessive-compulsive disorder (5 papers, 2022 to 2023). A disorder characterized by the presence of persistent and recurrent irrational thoughts (obsessions), resulting in marked anxiety and repetitive excessive behaviors (compulsions) as a way to try to decrease that anxiety. "Obsessive-compulsive disorders were similar with none of the results showing statistical significance, however, all showed a positive association with CRP." (PMID 35028602, 2022).
obstructive uropathy (5 papers, 2021 to 2024). "The AUC of CRP in the diagnosis of pyonephrosis was 0.82 (95%CI, 0.763-0.878) at the ideal cut-off value of 38.83." (PMID 38896174, 2024). "The findings of the multivariate LR analysis showed that hemoglobin and CRP were the only two independent risk variables for the incidence of pyonephrosis, there was no collinearity in the occurrence of pyonephrosis." (PMID 38896174, 2024).
orchitis (5 papers, 2016 to 2024). Inflammation of one or both testes due to viral or bacterial infections. "At the age of 8, P2 presented with severe abdominal pain, chest pain, dyspnea, and orchitis and got convulsion once; their laboratory tests showed elevated WBC (10,580 cells/μL; neutrophils 88%), CRP level (77.2 mg/L), ESR (76 mm/h), and SAA level (83.3 mg/L; normal range: 0–10 mg/L)." (PMID 37676738, 2023).
otitis media (5 papers, 2017 to 2023). Inflammation of the anatomical structures of the middle ear, which is most often caused by an infectious process. "The best model fit for antibiotic use on admission (c-index 0.896) was achieved for otitis media (OR 4.5, 95% CI 2.1–9.4), CRP on admission (OR 1.7, 95% CI 1.5–2.0), and septic appearance (OR 8.95, 95% CI 1.5–54.1)." (PMID 32807104, 2020). "In summary, we show that clinical appearance on admission, the presence of otitis media, but also a high CRP and the length of oxygen therapy are the main factors associated with antibiotic use in our cohort of in children below the age of 2 years with RSV or FLU infection." (PMID 32807104, 2020). "The best model fit for antibiotic use at any time point was achieved for the following factors (c-index 0.916): otitis media (odds ratio 8.33; 95% confidence interval 3.58–19.37), peak CRP (OR 1.77; 95% CI 1.54–2.04), and the length of oxygen therapy (OR 1.40; 95% CI 1.13–1.74)." (PMID 32807104, 2020). "The median peak CRP level was slightly elevated at 35 mg/L, whereas one-third had otitis media." (PMID 28095451, 2017).
overnutrition (5 papers, 2014 to 2024). An imbalanced nutritional status resulting from excessive intake of nutrients. "Environmental factors such as infections, overnutrition, and lack of physical activity are believed to contribute serum CRP levels although the mechanism is not properly understood." (PMID 26824043, 2016).
polycythemia (5 papers, 2014 to 2025). Abnormally high mass or concentration of red blood cells in the blood, either due to an increase in erythropoiesis or a decrease in plasma volume. "There is also evidence of blood and biochemical changes after envenomation, like polycythemia, increased C-reactive protein levels, decreased ATP in skeletal and cardiac muscles, and proteolytic effects." (PMID 39590501, 2024). "In thrombophilic condition such as essential thrombocythemia and polycythemia, high rate of thrombotic event is observed in the high CRP levels or low PTX3 levels." (PMID 25587447, 2014). "Furthermore, in our study, patients with polycythemia were younger, had a better nutritional status (higher BMI and albumin), lower inflammatory markers (CRP, PCT, G test, GM test), which might also be one of the reasons why they had a lower risk of adverse outcomes." (PMID 41179861, 2025).
primary sclerosing cholangitis (5 papers, 2017 to 2025). "A randomized controlled trial reported that high C-reactive protein (CRP) levels, primary sclerosing cholangitis comorbidity, and female sex were predictors of failure." (PMID 38166010, 2024).
psittacosis (5 papers, 2021 to 2025). "The laboratory data of patients in our paper showed normal or slightly elevated leucocytes, neutrophils, and PCT, along with high CRP levels, which are consistent with those usually showed in psittacosis." (PMID 34176434, 2021). "Patients with psittacosis have a high rate of severe disease, andNLR is superior in efficacy to PCT and hs-CRP in detecting severe conditions." (PMID 40990897, 2025). "It has been reported in the literature that patients with psittacosis have a normal WBC with a “left shift of the nucleus” and a significantly elevated CRP." (PMID 37772263, 2023). "Laboratory tests showed increased WBCs, neutrophils, NLR, hs-CRP, and PCT in patientswith severe psittacosis than that of the non-severe group and decreased Hb andPaO2/FiO2." (PMID 40990897, 2025).
retinal diseases (5 papers, 2021 to 2025). "The continued presence of a significant association between hs-CRP and DR after adjustment provides increased confidence for an independent association between systemic inflammation and retinal disease." (PMID 41159344, 2025). "Likewise, an elevated C-reactive protein (CRP) level, a common marker of systemic inflammation, has been shown to inhibit nitric oxide-mediated dilation in retinal arterioles through the stimulation of NADPH oxidases, creating superoxides, further supporting NADPH oxidases’ role in retinal diseases." (PMID 39203931, 2024).
SAPHO syndrome (5 papers, 2014 to 2023). SAPHO syndrome (acronym for Synovitis, Acne, Pustulosis, Hyperostosis and Osteitis) is an auto-inflammatory disease, mainly characterized by the association of neutrophilic cutaneous involvement and chronic osteomyelitis. "Studies have shown that from its onset, SAPHO syndrome is associated with an elevated erythrocyte sedimentation rate and increased C-reactive protein values." (PMID 25009594, 2014). "In the present case, ESR and hs-CRP were significantly elevated at admission, which indicated the active stage of SAPHO syndrome; levels were reduced to normal levels after treatment, suggesting remission of the disease." (PMID 36983699, 2023). "Some studies have demonstrated that erythrocyte sedimentation rate and CRP may be elevated for SAPHO syndrome, and our report also confirmed this." (PMID 30654792, 2019). "At present, although there are no specific markers for SAPHO syndrome evaluation, ESR and CRP may increase during the active phase." (PMID 36983699, 2023). "Moreover, the levels of C-reactive protein (CRP) and the erythrocyte sedimentation rate (ESR) are also elevated in most patients, but not in complete accordance with the activity of SAPHO syndrome." (PMID 33392854, 2021).
Schnitzler syndrome (5 papers, 2020 to 2025). A rare, underdiagnosed disorder in adults characterized by recurrent febrile rash, bone and/or joint pain, enlarged lymph nodes, fatigue, a monoclonal IgM component, leukocytosis and systemic inflammatory response. "Strasbourg diagnostic criteria” for Schnitzler syndrome (CRP—C-reactive protein, Ig—Immunoglobulin)." (PMID 40718535, 2025). "Schnitzler`s syndrome is a rare autoinflammatory disease characterized by urticarial rash, joint pain, recurrent fever, leucocytosis, elevated C-reactive protein (CRP), and monoclonal immunoglobulin (Ig)M or IgG gammopathy." (PMID 37063861, 2023). "Schnitzler syndrome is a rare autoinflammatory disorder characterized by urticarial rash, joint pain, recurrent fever, leucocytosis, elevated C-reactive protein (CRP) and serum amyloid A (SAA), and monoclonal IgM or IgG gammopathy." (PMID 37063861, 2023).
secondary hyperparathyroidism (5 papers, 2014 to 2025). Overproduction of parathyroid hormone in response to influence external to the parathyroid glands. "Exclusion criteria included acute or chronic bleeding, serum albumin < 35g/L, hypersensitive C-reactive protein (HsCRP) > 10 mg/L, and severe secondary hyperparathyroidism (iPTH ≥ 800 pg/mL)." (PMID 34629085, 2021).
Stillbirth (5 papers, 2017 to 2026). Death of the fetus in utero after at least 22 weeks of gestation. "Studies from India have reported that wood fuel use is associated with low birth weight, more frequent stillbirth and increased risk of preterm delivery, outcomes that are in turn associated with elevated CRP." (PMID 28571565, 2017). "The findings for the relationship of I-FABP and LPS IgA with stillbirth were consistent when additionally adjusting for CRP." (PMID 36130475, 2022). "Certain first-trimester AL biomarkers, notably CRP, BMI, DBP, SBP, HDL, and insulin, are significantly associated with HDP, but not with outcomes like preterm birth, SGA, or stillbirth." (PMID 41586415, 2025). "Findings revealed that individual components of AL, such as CRP, BMI, DBP, SBP, and HDL, and insulin during the first trimester were significantly associated with hypertensive disorders of pregnancy (OR: 2.5, 95% CI: 2.0–2.9) but not with preterm birth, small for gestational age, or stillbirth." (PMID 41586415, 2025).
stress-related disorder (5 papers, 2022 to 2025). Stress-related disorders are mental health disorders that are a result of an atypical response to both short and long-term anxiety due to physical, mental, or emotional stress. "In this review, we explore the role of CRP and IL-6 not only as biomarkers of systemic inflammation but also as active participants in the pathophysiology of neurodegenerative and stress-related disorders." (PMID 41373439, 2025). "However, we must take into account that non-cardiac stress-related disorders may be associated with higher inflammation markers (including CRP) and greater risk of cardiovascular diseases." (PMID 38398769, 2024).
thymoma (5 papers, 2016 to 2025). A neoplasm arising from the epithelial cells of the thymus. "To evaluate the possible association of increased CRP serum concentrations with proinflammatory cytokines we measured IL-6 and IL-1β serum concentrations in 39 patients with TETs (thymoma: n = 23; TC: n = 15) in comparison to age- and sex-matched volunteers." (PMID 28514756, 2017). "We utilized a mouse thymoma BW5147 reporter cell panel stably expressing chimeric human FcγR-CD3ζ-chain receptors to define the molecular requirements for FcγR crosslinking by C-reactive protein (CRP)." (PMID 40458392, 2025). "At one-way ANOVA CRP serum concentrations in patients with thymomas (n = 93; 0.62 ± 0.21 mg/dL), TCs (n = 30; 2.33 ± 0.7 mg/dL) and TNETs (n = 5; 0.90 ± 0.44 mg/dL) compared to controls were significantly different (p < 0.001)." (PMID 28514756, 2017). "Separate analysis of CRP serum concentrations of thymomas compared to controls and TNETs compared to controls by independent student`s t-test revealed significant differences (p = 0.010 and p = 0.016, respectively)." (PMID 28514756, 2017). "We detected significantly higher CRP serum concentrations in patients with B3 thymomas compared to patients with A/AB/B1/B2 thymomas (B3 thymomas vs. A/AB/B1/B2 thymomas: CRP 2.05 ± 1.14 mg/dL vs. 0.32 ± 0.049 mg/dL; p = 0.009)." (PMID 28514756, 2017). "We found the highest concentrations of pretreatment serum CRP in patients with TCs (2.33 ± 0.7 mg/dL) and the lowest CRP levels in WHO type AB and B2 thymomas (0.18 ± 0.03 mg/dL and 0.25 ± 0.08 mg/dL, respectively)." (PMID 28514756, 2017). "While CRP serum concentrations could not differentiate between TETs with poorer prognosis (B3 and TCs), thymoma types with better prognosis: A/AB/B1/B2 could be differentiated from those with poorer prognosis: B3 and TCs." (PMID 28514756, 2017).
Tricuspid regurgitation (5 papers, 2022 to 2023). Failure of the tricuspid valve to close sufficiently upon contraction of the right ventricle, causing blood to regurgitate (flow backward) into the right atrium. "In a multiple regression model, unfavorable lower FMD% was independently determined by higher age and BMI, elevated CRP, increased tricuspid regurgitation velocity, suggesting higher SPAP, and a thicker interventricular septum." (PMID 35456355, 2022).
valvular heart disease (5 papers, 2017 to 2025). "Moreover, NT-proBNP is established as a blood biomarker for the diagnosis and prognosis of HF, and CRP is identified as a common inflammatory factor in HF, both of which are elevated in patients with HF and valvular heart disease." (PMID 38654254, 2024).
viral respiratory tract infection (5 papers, 2022 to 2025). A respiratory tract infection caused by a virus. "FebriDx is a rapid point-of-care test combining qualitative measurements of C-reactive protein (CRP) and Myxovirus Resistance Protein A (MxA) using a disposable test device to detect and differentiate acute bacterial from viral respiratory tract infections." (PMID 38202172, 2023). "Procalcitonin (PCT) and CRP are non-specific markers of the host response to tissue injury and inflammation, and their serum concentrations usually are higher in bacterial than in viral respiratory tract infections." (PMID 38133281, 2023).
xerostomia (5 papers, 2016 to 2025). Dryness of the mouth resulting from reduced salivary secretion. "Previous studies have shown that HCQ can effectively relieve dry mouth symptoms in patients with pSS, improve fatigue status and reduce the levels of CRP and ESR; however, its impact on Bregs levels has not been fully investigated." (PMID 40678132, 2025).
abnormal glucose tolerance (4 papers, 2009 to 2019). "On the contrary, serum C-reactive protein concentrations increased in obese women compared to their non-obese counterparts and tended to increase (P = 0.079) in the women presenting with abnormal glucose tolerance, but were similar in PCOS and non-hyperandrogenic women." (PMID 19440331, 2009).
acute chest syndrome (4 papers, 2016 to 2022). A vaso-occlusive crisis of the pulmonary vasculature occurring in patients with sickle cell disease. "Such a result suggests that when the CRP level at admission is above this threshold, it might be reasonable bring up the possibility of an associated infection or an acute chest syndrome." (PMID 31546961, 2019). "It has also been reported that CRP level might be useful to anticipate the development of acute chest syndrome." (PMID 35159394, 2022). "Serum level of C-reactive protein (CRP)—the most commonly-assessed marker of acute and chronic inflammation—was associated with increased risk of vaso-occlusive crisis in SCA patients, thereby resulting in acute chest syndrome." (PMID 29083375, 2016).
Acute hepatitis (4 papers, 2022 to 2025). Acute hepatic injury resulting from inflammation typically accompanied by increased serum alanine transaminase activity. "The persistence of the symptoms, high levels of transaminases, coagulopathy, increased lymphocytosis, and C-reactive protein (CRP) in the blood suggested an acute hepatitis episode." (PMID 41019762, 2025). "Mortality rate, ICU LOS, hospital LOS, systemic inflammation (CRP and neutrophil downgrade), and acute hepatitis were significantly reduced." (PMID 36570123, 2022). "Mean CRP and fibrinogen levels were significantly different between HLH and non-HLH patients (169 vs 128 mg/L and 3.5 vs. 4.8 g/L, respectively, p < 0.001), and they were especially low in patients with acute hepatitis (mean, 81 mg/L and 2.7 g/L)." (PMID 36143085, 2022).
acute liver failure (4 papers, 2020 to 2025). Rapid deterioration of liver function causing encephalopathy and coagulopathy. "In patients with ACLF grade 2/3, we here observed even lower levels of circulating LBP despite increasing levels of CRP as in acute liver failure." (PMID 40317887, 2025). "In relation to the investigated factors and poorer outcomes, acute liver failure; platelet count; albumin level; ALT, AST, and LDH activities; and CRP concentration were associated with higher mortality." (PMID 33282888, 2020). "C-reactive protein (CRP) levels tended to be higher in acute liver failure (ALF) patients than in non-ALF patients." (PMID 33573054, 2021). "This patient, who had CRP levels between 120 and 150 during the critical period, did not develop shock, although he did develop acute liver failure." (PMID 33207759, 2020).
Ageusia (4 papers, 2022 to 2023). A rare condition that is characterized by a complete loss of taste function of the tongue. "The serum concentrations of inflammatory markers (IL-1β, TNF-α, and CRP) were higher in subjects with ageusia/hypogeusia than in subjects with normogeusia, but without any statistical significance." (PMID 36675526, 2023).
alcoholic cirrhosis (4 papers, 2016 to 2025). "In addition, a reduction of circulating levels of PDGF-BB, and increased levels of inflammatory markers such as CRP, IL-6 and TNFα, were observed in patients with alcoholic cirrhosis." (PMID 34884173, 2021). "In the present study, high circulating levels of CRP, IL-6 and TNF-α in the cirrhotic group are consistent with a chronic inflammatory state, which is typical for end-stage alcoholic liver cirrhosis." (PMID 34884173, 2021).
Anxiety Depression (4 papers, 2015 to 2023). "r: correlation coefficient, CI: 95% confidence interval, HADS: Hospital Anxiety Depression Scale, PSQI: Pittsburgh Sleep Questionnaire Index, CRP: C-reactive protein." (PMID 37644934, 2023). "The other assessments used are Hamilton Anxiety Depression Scale (HADS), World Health Organization Quality of Life (WHOQOL) scales, and C-reactive protein." (PMID 29953014, 2018).
aortic valve calcification (4 papers, 2015 to 2024). "The effect of C-reactive protein (CRP) gene rs1205 C>T polymorphism on the risk of severe aortic valve calcification * analyzed by logistic regression." (PMID 26473826, 2015). "In addition to its association with CRP levels, we detected a strong association between minor allele of rs1205 polymorphism and more severe aortic valve calcification." (PMID 26473826, 2015). "Carriers of the rs1205 T allele were characterized by elevated serum CRP levels (2.53 (1.51–3.96) vs. 1.68 (0.98–2.90) mg/L, p < 0.001) and a higher proportion of the severe aortic valve calcification (70.4% vs. 55.1%, p = 0.01) compared with major homozygotes." (PMID 26473826, 2015). "Data about the predictive role of CRP in AS or any valve disease in SSc have never been explored; nevertheless, data about the predictive role of CRP in calcific aortic valve disease or AS in the general population remain controversial." (PMID 39330332, 2024). "However, CRP does not predict disease progression of calcific aortic valve disease, although studies suggest that CRP gene variants may attenuate AS disease progression." (PMID 33808189, 2021).
Aphthous Stomatitis (4 papers, 2014 to 2022). "Also, acute phase reactants ESR and CRP levels were significantly higher and albumin and vitamin B12 levels were significantly lower in the aphthous ulcer group (p<0.05)." (PMID 24560378, 2014). "The goal of this study was to investigate whether there is a correlation between C-reactive protein to albumin ratio (CAR) and oral ulcer activity in patients with recurrent aphthous stomatitis." (PMID 31803551, 2019).